CTSS (cathepsin S)
Diseases named in the same sentence as CTSS in open-access papers (continued):
Sharing a sentence is not in itself a finding about the gene and the disease.
diabetes (26 papers, 2016 to 2026). "Increased CTSS expression in the serum of elderly people correlate with diminished insulin responsiveness and a heightened risk of type 2 diabetes mellitus." (PMID 39964999, 2025). "In our earlier studies, we found that the serum biomarker cathepsin S was associated with the risk of developing diabetes, probably by impairing insulin sensitivity." (PMID 38731158, 2024). "Modulated CTSS activity is also associated with pulmonary disease comorbidities, such as cancer, cardiovascular disease, and diabetes." (PMID 32398133, 2020). "CTSS may be involved in the early dysregulation of glucose and insulin metabolism as higher serum CTSS was associated with decreased insulin sensitivity and an increased risk for developing diabetes." (PMID 32398133, 2020). "In this report, we found a remarkable association between cathepsin S and the urine output of HPLBII-P not only in the subgroup of patients with diabetes mellitus but also in the whole ULSAM cohort of elderly men." (PMID 38731158, 2024). "Studies have revealed the significant involvement of CTSS in diseases such as Alzheimer’s disease, acute brain injury, stroke, diabetes, liver cancer, and inflammation." (PMID 38872630, 2024). "It has been demonstrated that CTSS expression is significantly higher in diabetes patients, and it serves as a robust biomarker for diabetes and atherosclerosis." (PMID 36982499, 2023). "On the other hand, inhibition of cathepsin S significantly decreases the response to antigens, and cathepsin S has been proposed as a therapeutic target for diabetes and certain auto-immune diseases such as asthma and psoriasis." (PMID 36979788, 2023). "Increased levels of CTSS in serum have been reported in many diseases, and relate to diabetes mellitus and heart disease." (PMID 36059966, 2022). "Cathepsin S is a potent cysteine protease active at neutral pH, enabling it to act extracellularly in degrading collagen and elastin, and has been noted to be elevated in diabetes." (PMID 41373586, 2025). "Since CTSS is upregulated under high blood glucose levels in vivo and in diabetic rat models, overexpression of CTSS can be considered a pathological factor in the development of diabetes." (PMID 36982499, 2023). "Hence, CTSS may be a novel target for preventing diabetes-induced microvascular complications." (PMID 36982499, 2023). "It is strongly associated with inflammatory matrix remodeling, including in rheumatoid arthritis and osteoporosis (preprint), but there is no literature on cathepsin S in diabetes bone disease." (PMID 41373586, 2025). "The changes seen for DKK1, cathepsin A, cathepsin S, cathepsin Z, and FGF23 that potentially favor a bone resorptive state may contribute to the resorptive effects of RANKL in diabetes." (PMID 41373586, 2025).
melanoma (24 papers, 2007 to 2025). A malignant, usually aggressive tumor composed of atypical, neoplastic melanocytes. "Namely, two MPRA-significant variants (rs2864871 and rs6700022) from the locus on chromosome band 1q21.3 were significant eQTLs for CTSS in melanocytes, where lower CTSS levels were correlated with melanoma risk." (PMID 32483191, 2020). "Genes in cluster 8 (GSTO2, LRRC34), 9 (CLPTM1L) and 10 (CTSS, SETDB1, ANXA9, GOLPH3L, HORMAD1, PPIL3, CASP9, ALS2CR12) underlie the association between melanoma and cancers." (PMID 38308491, 2024). "In human patients with melanoma, intralesional-BCG treatment was associated with enhanced M1 MΦ, mature DC, antigen processing and presentation, as well as with increased CTSS expression which positively correlated with patient survival." (PMID 35732347, 2022). "This modulation suggests that cathepsin S has a role in regulating cellular responses that could affect conditions like autoimmune liver disease and melanoma, demonstrating its broad functional implications in cellular signalling." (PMID 39074261, 2024). "Moreover, the strong positive correlation of CTSS expression with improved survival in patients with melanoma suggests its potential as a prognostic biomarker." (PMID 35732347, 2022). "Finally, elevated CTSS expression was observed in melanoma biopsies on intralesional BCG therapy, and positively correlated with improved survival in patients with melanoma." (PMID 35732347, 2022). "As representatively shown for three selected melanoma cell lines and HaCat as a control, the upregulation of HLA class II mRNA and surface expression by IFN-γ was associated with an increased expression of some HLA class II APM components, e.g., HLA-DO, HLA-DM, CIITA, CLIP and cathepsin S." (PMID 34359808, 2021). "The clinical relevance of these findings is reflected in increased CTSS expression observed in patients with melanoma treated with intralesional BCG, and the positive correlation between CTSS expression and improved survival in patients with melanoma." (PMID 35732347, 2022). "A range of other proteases such as Cathepsin S, complement Factor D and members of the Kallikrein protease family were also included in the proteome profiler arrays, however, none of these were detectable in the melanoma conditioned media." (PMID 36005056, 2022). "Moreover, we show that BCG hydrogel enhanced Cathepsin S (CTSS) expression and antigen presentation, which was also observed in intralesional BCG treated patients and correlated to improved survival in patients with melanoma." (PMID 35732347, 2022). "Our current studies suggest that the protease activities of cathepsin S, B, and D are increased in GILT-expressing melanoma cells as compared to melanoma cells lacking GILT (unpublished data)." (PMID 20016802, 2009).
Alzheimer disease (22 papers, 2012 to 2025). A progressive, neurodegenerative disease characterized by loss of function and death of nerve cells in several areas of the brain leading to loss of cognitive function such as memory and language. "In addition, the STAT3/CTSS signaling axis is implicated in diseases such as Alzheimer’s disease, diabetic nephropathy, and vascular calcification, highlighting its therapeutic potential in cardiovascular and neurological disorders." (PMID 40692794, 2025). "In clinical studies, an elevated plasma CTSS level was noted in patients with Alzheimer’s disease and was correlated with increased risks of immobility and mortality in older adults." (PMID 38725007, 2024). "Showing the roles of neuronal CTSS in the process of aging and Alzheimer's disease (AD)." (PMID 39453382, 2025). "Virobay’s oral inhibitors VBY-036 (phase I, neuropathic pain) and VBY-891 (phase II, psoriasis) exhibit tissue-specific targeting, with the latter favoring skin CTSS modulation, alongside preclinical VBY-825 for neuropathic pain and Alzheimer’s disease." (PMID 40692794, 2025). "Of these proteins, MSR1 and CTSS are also upregulated in a blood transcriptomic study of individuals with comorbid PTSD and Alzheimer’s disease." (PMID 35625844, 2022). "Notably, elevated CTSS expression was reported in the anterior lumbar spinal cord of ALS patients and brain tissue of patients with Alzheimer’s Disease." (PMID 33892821, 2021).
rheumatoid arthritis (22 papers, 2010 to 2025). A chronic, systemic autoimmune disorder characterized by inflammation in the synovial membranes and articular surfaces. "Recently, an increased RNA editing rate of Alu elements in CTSS 3′ UTR was shown to be associated with elevated CTSS gene expression in systemic sclerosis patients and rheumatoid arthritis patients." (PMID 37202785, 2023). "Both PSAP and CTSS were investigated if their expression in monocyte were changed by clinical conditions among 78 patients with rheumatoid arthritis in the dataset." (PMID 40581066, 2025). "As a result, inhibition of CTSS proved to have an anti-inflammatory therapeutic effect toward lupus progression, rheumatoid arthritis, Sjögren’s syndrome, encephalomyelitis and autoimmune-triggered inflammatory responses in macrophages." (PMID 36674470, 2023). "Cathepsin S, on the other hand, is a target for the treatment of inflammatory diseases, such as rheumatoid arthritis and pulmonary fibrosis, and several cathepsin S inhibitors, e.g., petesicatib (Roche, Basel, Switzerland), have shown potential in clinical trials." (PMID 36012257, 2022). "Since CTTS responses are triggered by inflammatory stimuli and CTSS deficiency can attenuate MHC class II presentation, many investigators have focused on CTSS as a target in immunological disorders, such as lupus, rheumatoid arthritis, Sjögren’s syndrome and encephalomyelitis." (PMID 32398133, 2020). "Inflammatory mediators promote cathepsin S secretion from macrophages and microglial cells, and there is increased cathepsin S activity in inflamed tissues, including synovial fluid from patients with rheumatoid arthritis and colonic secretions from mice with colitis." (PMID 24860547, 2014).
lung carcinoma (21 papers, 2001 to 2025). "Cathepsin B or cathepsin S has been implicated in the progression of various human cancers, including bladder, breast, prostate and lung cancers." (PMID 21595995, 2011). "Further work is needed to delineate the role of CTSS in lung cancer and whether there is an association between elevated CTSS in COPD and lung cancer initiation and progression." (PMID 32398133, 2020). "Decorin, a proteoglycan of the interstitial matrix, is degraded by CTSS in lung cancer and may be associated with lung cancer pathology." (PMID 32398133, 2020). "CTSS levels are significantly elevated in the sera of patients with gastric, esophageal, liver, colorectal, nasopharyngeal, and lung cancers." (PMID 38883596, 2024). "Given its ability to remodel the ECM, it is not surprising that there is a vast amount of research on the role of CTSS in cancer, however, data specific to lung cancer is relatively limited." (PMID 32398133, 2020). "Increased expression of CTSS is correlated with poor prognosis in the context of some cancers (breast and colorectal cancer) but also correlated with better outcome in others (lung cancer)." (PMID 32483191, 2020). "The clinical data indicated that degradation of decorin by cathepsin-S is an important part of the pathology of lung cancer and IPF." (PMID 28793886, 2017). "In addition, studies have indicated that CTSB and CTSS mediate cancer progression and metastasis in lung cancer, renal cancer, and gastric cancer." (PMID 32331211, 2020). "Cathepsin S (Ctss), a key enzyme in major histocompatibility complex class II (MHC-II) mediating antigen presentation, might be involved in malignant progression of lung cancer." (PMID 25907256, 2015).
viral infection (20 papers, 2011 to 2026). "Pathologically, while the role of CTSS in antigen presentation has long been recognized, CTSS has been implicated in the pathogenesis of some viral infections." (PMID 41258714, 2026). "Abnormal expression and/or activity of CTSs has been associated with a variety of human diseases, including inflammatory and cardiovascular diseases, neurodegenerative disorders, diabetes, obesity, cancer, kidney dysfunction, viral diseases and many others." (PMID 34443335, 2021). "The involvement of cathepsin S, transgelin 2 and C-X-C motif chemokine 13 with other infections provides a foundation for the evaluation of the potential role of these proteins in E. coli UTI pathophysiology while other proteins have been linked to viral infections." (PMID 32628701, 2020). "In viral infections, inhibiting the expression of miR-369-3p dramatically reduces the expression of antiviral response genes, including CCL3, CCL5, CTSS, CXCL11, and IRF3." (PMID 37509488, 2023).
Sjögren’s syndrome (19 papers, 2010 to 2025). "Cathepsin S inhibition in Sjögren syndrome reduces the auto-antibody production and alleviates the lymphocytic infiltration of salivary and lacrimal glands." (PMID 40376613, 2025). "From a testosterone perspective, higher testosterone prevents expression of cathepsin S and protects males from Sjogren's syndrome." (PMID 36793337, 2023). "The inhibition of cathepsin S in experimental Sjögren syndrome reduced both the autoantibody production and the lymphocytic infiltration of salivary and lacrimal glands." (PMID 37745290, 2023). "Testosterone can suppress some immune-related genes such as cathepsin S in lacrimal glands from female mouse models of Sjögren's syndrome." (PMID 36793337, 2023). "Recently, CTSS activity was observed to be elevated in Sjögren’s syndrome patient tears, which results in tear protein degradation." (PMID 32398133, 2020). "Systemic or topical administration of a CTSS inhibitor reduced symptoms in a mouse model of Sjögren’s syndrome." (PMID 32398133, 2020). "Cathepsin S (CTSS) is highly increased in Sjögren’s syndrome (SS) patients tears and in tears and lacrimal glands (LG) of male non-obese diabetic (NOD) mice, a murine model of SS." (PMID 31267034, 2019). "Additional genes of interest included that for cathepsin S, which is significantly increased in the tears of Sjögren syndrome patients, and is more highly expressed in lacrimal tissues of female MRL/lpr mice (CodeLink = 2.85-fold; Affymetrix = 3.03-fold)." (PMID 30481277, 2018). "Elevated cathepsin S activity in tears has been proposed as a potential biomarker for dry eye and Sjögren syndrome, as published data have shown increased activity in non–Sjögren syndrome dry eye patients compared to healthy controls." (PMID 37540176, 2023). "The source of increased cathepsin S levels in aged tears is most likely dysregulated exocytosis of endolysosomal vesicles in the lacrimal gland acinar cells, as it has been demonstrated to occur in a murine Sjögren syndrome model." (PMID 37540176, 2023). "Cathepsin S (CTSS) activity is elevated in Sjögren’s Syndrome (SS) patient tears." (PMID 30038391, 2018). "Cathepsin S (CTSS) activity is increased in tears of Sjögren’s syndrome (SS) patients." (PMID 30423938, 2018). "In addition, expression of several genes known to be dysregulated in Sjögren's syndrome: CTSS, MHC-II, MMP9, Rab proteins (Rab3D, Rab27A, and Rab27B), IL12α, IFN-γ, TNF-α, and aquaporin 5 (Aq5), and the cholinergic muscarinic M3 receptor (M3R) were quantitatively measured using qPCR." (PMID 28348600, 2017). "By contrast, a recent phase II study that evaluated a 12-week-long daily oral intake of RO5459072 cathepsin S inhibitor in patients with Sjögren syndrome did not detect a clinical benefit." (PMID 37540176, 2023). "A previous study showed that CTSS-mediated induction of CX3CL1 might contribute to the ocular surface and lacrimal glands inflammation in Sjögren's syndrome with a 4.5-fold increase in CX3CR1-expressing macrophages." (PMID 33553270, 2020).
glioblastoma (18 papers, 2014 to 2025). The most malignant astrocytic tumor (WHO grade IV). "In agreement with this, our data on defective migration and invasion capacities in glioblastoma cells expressing miR-7 could possibly correlate with our findings showing a reduction in MMPs, CTSs and SERPINs, all linked to ECM degradation." (PMID 40813676, 2025). "Downregulation of cathepsin S was previously reported to promote apoptotic cell death in hepatocellular carcinoma and glioblastoma cells." (PMID 35455407, 2022). "Similar effects on the inhibition of CTSS-induced apoptosis were observed in human glioblastoma and renal carcinoma cells." (PMID 36289617, 2022). "Autophagic flux test confirmed that knockdown of CTSS in glioblastoma contribute to blockade of autophagic flux." (PMID 33425712, 2020). "CTSS is overexpressed in different cancer types (including astrocytomas), and is reported to be an independent prognostic factor of survival for glioblastoma." (PMID 27891063, 2016). "ROS-mediated PI3K/AKT/mTOR/p70S6K signaling pathways was critical to the effects of cathepsin S on the regulation of autophagy and apoptosis in human glioblastoma cells." (PMID 26058063, 2015). "In autophagy-inhibitory glioblastoma cells by treating an autophagy inhibitor 3-MA or Beclin-1 shRNA, cathepsin S inhibition-induced apoptosis were drastically reduced." (PMID 25402829, 2014). "In cathepsin S-inhibitory glioblastoma cells, ROS-mediated PI3K/AKT/mTOR/p70S6K signaling pathway was inhibited and c-Jun N-terminal kinase (JNK) was activated." (PMID 25402829, 2014). "Therefore, it is promising for further studies on CTSS inhibitors in glioblastoma and other cancers." (PMID 33613746, 2021). "In our study, we found that TGF-β could increase the expression of CTSS in glioblastoma and, meantime, induce expression levels of mesenchymal proteins (N-cadherin, Vimentin), and decrease E-cadherin level in glioblastoma." (PMID 33613746, 2021). "We used to find that inhibition of CTSS in glioblastoma cell lines could suppress the PI3K/AKT/mTOR pathway in previous study." (PMID 33613746, 2021). "Collectively, these data illustrated the autophagic flux in glioblastoma could be blocked in long-term CTSS inhibition." (PMID 33425712, 2020). "Cathepsin S plays an active role in angiogenesis by generation of proangiogenic peptides, promotes tumor growth, and has been shown to be a significant prognostic factor for patients with glioblastoma." (PMID 30669448, 2019). "Taken together, these results suggest that CDC7 inhibition may suppress glioblastoma growth through CTSS." (PMID 27891063, 2016). "Cathepsin S (CTSS) expression is linked with tumor progression and poor outcome in glioblastomas." (PMID 27344170, 2016). "Cathepsin S, a lysosomal cysteine protease, was reported to overexpress in glioblastoma cells." (PMID 25402829, 2014). "Since TGF-β is one of the most important factors in tumor microenvironment and played a pivotal role in tumor mesenchymal transition, here we wondered whether TGF-β induced invasive growth and endothelial-mesenchymal state in glioblastoma and the potential role of CTSS in this process." (PMID 33613746, 2021). "In addition, high CTSS expression in glioblastoma shows a poor prognosis." (PMID 31138312, 2019). "Inhibition of cathepsin S can also inhibit TGF-β-mediated EMT through the PI3K/AKT/mTOR signaling pathway, as well as the invasive growth of glioblastoma." (PMID 37398678, 2023). "However, the role of CTSS in TGF-β-induced EMT in glioblastoma was remained unknown." (PMID 33613746, 2021). "Cathepsin S (CTSS), a lysosomal cysteine protease, is overexpressed in various cancers, including glioblastoma (GB)." (PMID 33425712, 2020). "Notably, our results suggest that CDC7 inhibition may suppress glioblastoma growth through CTSS." (PMID 27891063, 2016). "Inhibition of cathepsin S by its inhibitor Z-FL-COCHO (ZFL) can induce autophagy and mitochondrial-based apoptosis in glioblastoma cells." (PMID 25402829, 2014).
glioblastoma (continued). "In a 2014 study, experimental results revealed that the use of the cathepsin S inhibitor ZFL resulted in the upregulated expression of the autophagy-related protein LC3 and the phosphorylation of AKT, mTOR, and p70S6K in human glioblastoma cells, thereby promoting autophagy and apoptosis." (PMID 37398678, 2023). "Taken together, our results demonstrated that inhibition of CTSS could reverse TGF-β-mediated EMT and tight junction proteins turnover in human glioblastoma cell lines through suppressing the PI3K/AKT/mTOR pathway." (PMID 33613746, 2021). "Furthermore, inhibition of CTSS could reverse TGF-β-induced epithelial-to-mesenchymal transition (EMT) and restore TGF-β-triggered tight junction proteins turnover, thus decreasing glioblastoma cell mobility." (PMID 33613746, 2021).